INS (insulin)
Diseases named in the same sentence as INS in open-access papers (continued):
Sharing a sentence is not in itself a finding about the gene and the disease.
diabetes (continued). "Possible mechanisms of action may be the stimulation of insulin release from remaining pancreatic β‐cells, the inhibitory activity of α‐glucosidase, improving general clinical conditions by minimizing the weight loss characteristic of diabetes induction, and the antioxidant effects of the extract." (PMID 39055210, 2024). "For people living with type 1 diabetes (T1D), achieving financial independence can be particularly daunting given the high costs of insulin and other diabetes supplies and, in the United States, an employment-based insurance model with minimal safety net." (PMID 38344219, 2024). "Since ABCC8-MODY can present initially with severe hyperglycemia with classical symptoms of diabetes, it is often inappropriately treated with an insulin-based regimen when undiagnosed, typically with poor glucose control." (PMID 38980630, 2024). "At that account creation or at a later time, the patients record diabetes oral medication or insulin dosage, clinical profiles, and demographic information." (PMID 38617952, 2024). "Several studies have also indicated that insulin treatment can attenuate diabetes-related brain-resident mitochondrial alterations, emphasizing the role of insulin in preserving mitochondrial functions." (PMID 38843768, 2024). "In a second report from that institution by Balasubramanyam, with a larger study group of 294 individuals (135 with newly diagnosed diabetes), 31% of the cohort were successfully withdrawn from insulin therapy and remained off insulin at 12 months." (PMID 38240751, 2024). "R.intestinalis can augment IL-22 synthesis, an anti-inflammatory cytokine acknowledged for reinstating insulin sensitivity and alleviating diabetes." (PMID 39692821, 2024). "Lastly, patient heterogeneity across different regions and the potential beneficial outcomes in patients with diabetes receiving insulin or other anti-inflammatory drugs should be considered." (PMID 38880917, 2024). "Late treatment with WJMSCs-CM and insulin slightly ameliorated diabetes-induced histological changes in the testis." (PMID 39391856, 2024). "We also studied only a subset of all insulin-dependent individuals with diabetes due to the prespecified inclusion criteria." (PMID 39141389, 2024). "Under pathological conditions, such as diabetes or heart failure, the transduction and action of insulin signals are modified." (PMID 39026321, 2024). "Diabetes significantly raises the vulnerability of the heart to I/R injury due to disrupted glucose and lipid processing, impaired insulin sensitivity and metabolic signaling, and increased inflammatory responses." (PMID 39538244, 2024). "Diabetes mellitus is a long‐term metabolic condition characterized by elevated blood glucose levels due to low insulin production or the body's inability to use insulin effectively." (PMID 39135385, 2024). "Diabetes therapy includes insulin and oral antidiabetic medications such as sulfonylurea, biguanides, α-glucosidase inhibitors, and glinides." (PMID 38891245, 2024). "Increases in cardiovascular disease, renal disease, stroke, ophthalmologic disease, obesity, and insulin use will increase the economic burden of diabetes and negatively impact the quality of life of those with diabetes." (PMID 38667608, 2024). "Diabetes was induced in Wistar rats using alloxan, which induces diabetes by damaging insulin-secreting pancreatic β cells, resulting in a decrease in endogenous insulin release and a decrease in GLU utilization by tissues, leading to hyperglycemia." (PMID 39338300, 2024). "Out of the 3,934 articles reviewed, 11 were selected, focusing on insulin sensitivity/resistance, diabetes incidence, and BMI changes with GAHT." (PMID 38738018, 2024). "More than 100 years after its discovery, many people with T1D die because they cannot access or afford insulin and other essential diabetes supplies." (PMID 38711747, 2024).
diabetes (continued). "These advancements promise to optimize insulin dosing, prevent hypoglycemic events, and ultimately enhance diabetes patients’ standard of life." (PMID 39686207, 2024). "With the increasing recognition of disease heterogeneity, insulin secretion has been used as a key feature in the subclassification of pre-diabetes and diabetes." (PMID 39013634, 2024). "The World Health Organization (WHO) states that diabetes is a chronic illness brought on by insufficient insulin production by the pancreas or improper insulin utilization by the body." (PMID 39125010, 2024). "The sodium-glucose cotransporter 2 (SGLT2) inhibitors are essential for treating diabetes in lipodystrophic patients due to their insulin-independent effect and notable cardio-renal benefits." (PMID 39398333, 2024). "Diabetes mellitus (DM) is a metabolic disorder characterized by chronic hyperglycemia and impaired metabolism of carbohydrates, lipids, and proteins due to defects in insulin secretion, insulin action, or both." (PMID 39104663, 2024). "Diabetes mellitus represents a significant global health challenge, characterized by impaired insulin production and action, leading to elevated blood glucose levels." (PMID 39435211, 2024). "Hyperglycemia in diabetes primarily results from insulin resistance, where tissues such as muscle and adipose fail to respond adequately to insulin." (PMID 39483560, 2024). "Many efforts have been undertaken to improve diabetes management, mainly focused on continuous glucose monitoring and developing smart insulin delivery systems." (PMID 38667679, 2024). "This affects normal insulin secretion and blood glucose regulation, potentially contributing to the development of diabetes." (PMID 39397263, 2024). "Diabetes mellitus (DM) is a persistent diverse metabolic disorder that has become a global epidemic and is principally caused by low synthesizing (availability) endogenous insulin from beta-cells of the pancreas and reduced sensitivity." (PMID 39421288, 2024). "Type 2 diabetes mellitus is a global health concern characterized by insulin resistance and impaired insulin secretion." (PMID 39463653, 2024). "Our diabetes cohort included only three women with pre-existing diabetes and only eight women (12%) who received insulin for diabetes." (PMID 39627143, 2024). "Diabetes mellitus (DM) is a chronic metabolic disorder characterized by impaired glucose metabolism, leading to hyperglycemia and insulin resistance." (PMID 38371125, 2024). "There were 323 patients with pharmacological diabetes treatment, including 186 treated by insulin and other antidiabetics, 35 only with insulin and 102 only with other antidiabetics." (PMID 38849653, 2024). "Diabetes is a persistent medical condition marked by elevated blood sugar levels due to insulin resistance, reduced sensitivity of target cells to insulin, and disruptions of carbohydrate metabolism." (PMID 38474747, 2024). "Diabetes mellitus is a disease characterized by long-term abnormalities in sugar metabolism due to the decreased secretion of insulin and increased insulin resistance." (PMID 39684854, 2024). "Studies have demonstrated that betalains can effectively lower blood glucose levels, enhance insulin secretion, and reduce oxidative stress, positioning them as a valuable functional food component for diabetes control." (PMID 39682981, 2024). "Traditional insulin pump screens serve as one of the biggest accessibility barriers for BLV people with diabetes." (PMID 39738754, 2024). "Low-carbohydrate diets have also been shown to improve glucose control and reduce the insulin requirement in people with type 1 diabetes, and low-carbohydrate diets were often used to treat diabetes prior to the discovery of insulin." (PMID 38794685, 2024). "Insulin glargine and insulin degludec are long-acting basal insulins that are used to treat type I and II diabetes." (PMID 38213906, 2024).
diabetes (continued). "Diabetes mellitus, a global health challenge characterized by chronic hyperglycemia due to impaired insulin secretion, insulin action, or both, is often managed with synthetic drugs that can cause significant side effects." (PMID 39452489, 2024). "This will subsequently improve diabetes outcomes via diet, physical exercise, and, if necessary, diabetic medication or insulin injections." (PMID 39273732, 2024). "On the other hand, the treatment of diabetic rats with sarpogrelate or insulin was found to attenuate diabetes-induced alterations in high-energy phosphate stores as well as changes in MT state 3 respiration and oxidative phosphorylation." (PMID 39057635, 2024). "Despite over a century of insulin therapy and recent advances in glucose monitoring, diabetes and its complications remain a significant burden." (PMID 39560873, 2024). "In the first set, age, BMI, WC, diabetes duration, daily insulin dose, eGFR, and eGDR were included as independent variables." (PMID 39335526, 2024). "The incident diabetes group had increasing plasma glucose, decreasing glycine and elevated insulin and glucagon levels." (PMID 39078488, 2024). "The inactivation of miR-142-3p/-5p and miR-155 in β cells leads to increased insulin levels, decreased insulitis scores, reduced inflammation, and provides protection against diabetes development in NOD mice." (PMID 38720885, 2024). "Diabetes mellitus (DM) is a group of chronic metabolic conditions defined by defects in insulin production, sensitivity, or both, resulting in hyperglycemia." (PMID 38931292, 2024). "Studies in rat models that mimicked diabetes mellitus type 1 (streptozotocin-induced) and diabetes mellitus type 2 (high-fat diet-fed rats) observed that the daily administration of apelin-13 ameliorated insulin sensitivity and decreased plasma glucose levels." (PMID 39457235, 2024). "Inadequate insulin in diabetes damages the HPG axis, decreasing GnRH, FSH, LH, and testosterone, leading to testicular atrophy, seminiferous tubules damage, and spermatogenic cell impairment." (PMID 39391856, 2024). "Diabetes occurs in cases of untreated IR, and these patients require more insulin to transport glucose." (PMID 39600764, 2024). "Over 60% of the cohort had hypertension and nearly 20% had diabetes; of these, over 70% were prescribed oral medication and/or insulin." (PMID 38671852, 2024). "Diabetes is a metabolic disease characterized by hyperglycemia due to impaired insulin secretion, activity, or both." (PMID 39408216, 2024). "The cessation of insulin treatment is a crucial component in enhancing the overall quality of life of individuals with diabetes." (PMID 38800472, 2024). "Our comparative study underscores the diverse landscape of insulin pumps and the continuous innovations aimed at providing tailored solutions for individuals with diabetes." (PMID 39065641, 2024). "The prospect of being able to efficiently inject large plasmids in insulin-producing beta cells is very attractive for diabetes research." (PMID 39010923, 2024). "In patients with diabetes, synthesis of ATP was significantly reduced or failed in response to insulin infusion owing to the reduction in the number of mitochondria in skeletal muscle." (PMID 37512131, 2023). "Attenuation of meta-inflammation and impaired insulin/IGF signalling by RAGE-targeted agents can be potentially exploited for optimal control of diabetes- and obesity-related cancers." (PMID 37970208, 2023). "These limitations have drawn the attention of diabetes researchers, who developed a variety of research methodologies ranging from insulin engineering to developing new delivery systems." (PMID 36769081, 2023). "Insulin-stimulated glycogen synthesis is reduced in insulin-resistant states such as obesity, diabetes, and the combined obesity–diabetes syndrome." (PMID 36980862, 2023).
diabetes (continued). "In this paper, we examine prescriptions of insulin and insulin analogues, as an indicator of diabetes requiring insulin therapy, in six European regions over a 15-year period for children with CAs compared with a cohort of reference children without CAs." (PMID 36869270, 2023). "Dysregulation is a major contributor to the glycemic response seen in uncontrolled diabetes, as the insulin signaling pathway regulates the transport of glucose in hepatic cells." (PMID 37762060, 2023). "As a metabolic disease, diabetes is characterized by defective insulin secretion or insulin dysfunction leading to impaired islet beta cell function." (PMID 36632457, 2023). "The strength of the current meta-analysis was the use of the recent definition of diabetes remission, the assessment of prolonged remission and relapse rate, and the assessment of insulin and GLIP-1 agonists use." (PMID 36829204, 2023). "The impaired insulin action in the liver, muscle, and adipose tissue, or insufficient secretion of insulin from the pancreatic β-cells, or both, contribute to the onset and progression of diabetes." (PMID 36771665, 2023). "This study aims to compare the simplicity, convenience, safety, and cost-effectiveness of insulin pens versus syringe devices in patients with type 2 diabetes mellitus (T2DM)." (PMID 36782190, 2023). "Out of an overall population of 13,133 patients, 2885 had diabetes (22.0%), 605 of whom (21.0%) were on insulin." (PMID 35976428, 2023). "These ranged from how potential pregnancy complications related to diabetes were discussed to the way advice or lack thereof was delivered regarding insulin pump settings during labour, among others." (PMID 37131168, 2023). "The combination of oral anti-diabetic agents with insulin can lower glycemic index and improve clinical outcomes, reducing diabetes-related health complications." (PMID 38021574, 2023). "Ins2Akita is a diabetes mouse model of mutant INS-gene induced diabetes of youth (MIDY), in which a spontaneous Cys96Tyr mutation in insulin 2 results in protein misfolding." (PMID 37522959, 2023). "The findings indicated that participants who practiced time-restricted eating experienced greater insulin sensitivity and reduced insulin amounts, suggesting its potential in managing diabetes, a critical aspect of diabesity." (PMID 38201865, 2023). "Targeting Different Mechanisms; diabetes medications work through various mechanisms, such as improving insulin sensitivity, increasing insulin secretion, reducing glucose production by the liver, or slowing down carbohydrate absorption." (PMID 37998569, 2023). "Befristungen sind für Menschen mit Diabetes mellitus, die mit Insulin oder anderen Medikamenten mit Hypoglykämierisiko behandelt werden, in der FSG-GV ausdrücklich geregelt." (PMID 37101052, 2023). "Anti‐insulin antibodies should be considered in insulin‐treated diabetes with unexplained glycaemic lability." (PMID 37562398, 2023). "The complexity of the human insulin system and the evolving nature of AI technology necessitate collaboration with diabetes specialists." (PMID 38161783, 2023). "Six managed their diabetes with an insulin pump, whereas four administered insulin with multiple daily injections." (PMID 36674378, 2023). "The increase of toxic metabolites in the β-cells of the pancreatic islet decreases insulin production and increases β-cell apoptosis, accelerating the development of diabetes." (PMID 38136211, 2023). "Our work provides comprehensive insight into understanding the mechanisms of insulin secretion and potential therapeutic targets for diabetes from the perspective of protein PTMs." (PMID 37601108, 2023). "The adipose tissue is one of the tissues that plays a crucial role in type 2 diabetes mellitus, specifically its insulin signaling." (PMID 36902049, 2023). "Although multifactorial, this disparity reinforces the need to improve access to diabetes education, blood glucose monitoring, skilled health care, and insulin." (PMID 36780227, 2023).
diabetes (continued). "Continuous glucose monitoring in patients with diabetes, including glucose variability and glucose prediction, providing information for insulin dosing." (PMID 37781727, 2023). "To identify metabolic variables that were predictive for the development of diabetes, we ran a multivariate Cox model including sex, BMI, fasting plasma glucose, insulin, C-peptide concentrations and fasting ISR." (PMID 36459177, 2023). "Continuous Glucose Monitoring (CGM) is a key tool for insulin-treated people with diabetes (PwD) measuring interstitial glucose level on a near-continuous basis, and providing information about glucose trend and rate of change." (PMID 37676398, 2023). "Numerous small molecules of GKAs have been developed in the past 20 years, based on the premise that they will stimulate insulin secretion and enhance hepatic glucose uptake in diabetes." (PMID 39872624, 2023). "CRISPR-Cas9 correction of the mutation of the patient’s IPSC-derived β cells rescued streptozocin-induced diabetes in mice and restored insulin secretion, showing the proof of the concept." (PMID 37759745, 2023). "Diabetes was defined as fasting blood sugar ≥ 126mg/dL, or glycohemoglobin ≥ 6.5%, or 2-hour Oral Glucose Tolerance Test blood sugar ≥ 200mg/dL, or taking hypoglycemic agent and insulin, or self-reported diabetes mellitus." (PMID 37310940, 2023). "While CGMs and insulin pumps have been significant innovations in diabetes care, the latest frontier is the development of wearable insulin biosensors that combine the benefits of both technologies." (PMID 38239544, 2023). "For patients with diabetes aged ≥ 10 years who self-inject insulin, the DSI was a viable and accurate method for quantifying discomfort associated with insulin injection." (PMID 37474582, 2023). "The autologous transplant of islet cells from the pancreas, with subsequent maintenance of optimal conditions for islet engraftment, is aimed at potentially (or partially) mitigating insulin-dependent post-pancreatectomy diabetes mellitus." (PMID 37176759, 2023). "Diabetes mellitus (DM) is a metabolic disease characterized by high blood glucose levels due to reduced insulin secretion or action." (PMID 37046962, 2023). "An obvious example of this can be seen with continuous glucose monitoring units for patients with diabetes, which provide a regular source of data that can be implemented immediately to adjust insulin therapy." (PMID 37646309, 2023). "Diabetes mellitus is a disease characterized by high blood glucose levels, either because of an inability to produce insulin or because the body is resistant to its effect." (PMID 38004438, 2023). "miRNAs are also involved in glucose homeostasis and regulate the expression of genes involved in diabetes-relevant pathways like the insulin signaling pathway." (PMID 38096208, 2023). "The final Model 3 was adjusted for age, sex, BMI, smoking, alcohol drinking, exercise, income status, hypertension, estimated glomerular filtration rate, fasting glucose levels, use of insulin, duration of diabetes, and use of statin." (PMID 37622547, 2023). "Diabetes mellitus, as a significant global health threat, is a cluster of MetS identified with hyperglycemia and destruction of cellular resistance to both insulin and insulin secretion." (PMID 37396948, 2023). "Compared to patients without DR, patients with DR were older (60 years versus 57 years, P < 0.05), had longer diabetes duration (10 years versus 4 years, P < 0.001) and higher frequency of insulin therapy." (PMID 36922809, 2023). "We extracted data from the Medical Expenditure Panel Survey (2009–2018) to document trends in the expenditure of insulin among people with diabetes." (PMID 36751859, 2023). "Clinical trials found that NEP inhibition resulted in reduced hemoglobin A1c (HbA1c), fewer new-onset diabetes, and less insulin therapy in patients with diabetes." (PMID 37065764, 2023).